HMGB1 (high mobility group box 1)
Diseases named in the same sentence as HMGB1 in open-access papers (continued):
Sharing a sentence is not in itself a finding about the gene and the disease.
brain edema (13 papers, 2013 to 2024). Increased intracellular or extracellular fluid in brain tissue. "As an early proinflammatory mediator, HMGB1 can promote neuroinflammation and microglial activation and aggravate cerebral edema and brain injury after ICH." (PMID 37191423, 2023). "Previous studies have demonstrated involvement of HMGB1 with astrocytes following injury, and the development of cerebral oedema post-TBI has been attributed to this." (PMID 33096930, 2020). "TBI-induced microglial activation and increased expression of inflammatory mediators (HMGB1, TNF-α, IL-1β, IL-6) in the brain have been associated with cerebral edema and neurological deficits." (PMID 32610502, 2020). "Anti-HMGB1 antibodies also prevented the increase in permeability of the BBB protecting the recipient from brain edema, inhibited activation of microglia and release of TNF-α and iNOS, while suppressing the activity of MMP-9." (PMID 29054968, 2017). "Interacting with other proinflammatory cytokines, extracellular HMGB1 aggravates inflammation and worsens injury in the ischemic brain, which further results in the up-regulation of aquaporins and exacerbation of brain edema." (PMID 29054968, 2017). "This suggests that the slight elevation in AQP4 levels, induced by the anti-HMGB1 mAb in the present study, may facilitate the recovery phase of brain edema." (PMID 38892076, 2024). "Furthermore, anti-HMGB1 McAb inhibits the development of brain edema through the protection of the blood–brain barrier and efficient clearance of circulating HMGB1." (PMID 24065095, 2013). "One classic example of DAMP release is high mobility group protein B1 (HMGB1); HMGB1 stabilizes nucleosomes under normal conditions but is greatly upregulated after injury and associated with elevated intracranial pressure in TBI patients as well as cerebral edema after moderate TBI in mice." (PMID 36894951, 2023). "The impact of HMGB1 upon neurones has been studied, and the inflammatory cascades induced by this DAMP have been shown to result in worsening cerebral oedema, raised intracranial pressure, and neuronal death." (PMID 33731757, 2021). "Glycyrrhizin treatment ameliorated TBI-induced brain edema and beam walking distance, inhibited the translocation of HMGB1 and down-regulated TBI-induced up-regulation of HMGB1, RAGE, TLR4, and NF-κB." (PMID 32610502, 2020). "We therefore propose that inhibition of HMGB1 could lead to reduction in AQP4 and hence reduction in brain edema." (PMID 29054968, 2017). "Anti-HMGB1 treatment partially reversed the decrease in AQP4 levels, suggesting its potential role in mitigating brain edema, but did not significantly affect the reduction in PAR-1 levels." (PMID 38892076, 2024).
cardiomyopathy (13 papers, 2012 to 2024). A disease of the heart muscle or myocardium proper. "Therefore, we used a series of experiments in vivo and in vitro to explore whether the regulation of HMGB1 is implicated in the role of DXZ in DOX-induced cardiomyopathy." (PMID 34336950, 2021). "In experimental models of cardiomyopathies induced by various stimulants, the inhibition of extracellular HMGB1 was found to be cardioprotective and reduce inflammation." (PMID 37484982, 2023). "The protective effect of dexrazoxane in the reduction of cytotoxicity in DOX-induced cardiomyopathy in rats was proven to inhibit ferroptosis by regulating high mobility group box 1 (HMGB1)." (PMID 36120592, 2022). "Inhibition of extracellular HMGB1 in experimental models of myocardial ischemia/reperfusion injury, myocarditis, cardiomyopathy induced by mechanical stress, diabetes, bacterial infection or chemotherapy drugs reduces inflammation and is protective." (PMID 35340325, 2022). "Various studies have shown the critical roles of extracellular HMGB1 in cardiovascular diseases, including myocarditis and cardiomyopathies." (PMID 33198253, 2020). "Higher expression of cardiac HMGB1 exerts a protective effect in the pathogenesis of Dox-induced cardiomyopathy." (PMID 30306212, 2019). "Therefore, DXZ has protective effects on ferroptosis and cardiomyopathy in rats through regulating HMGB1." (PMID 34336950, 2021). "However, a recent study showed that Hmgb1 can upregulate the expression of Hspb1 and attenuate the cardiomyocyte apoptosis associated with DOX-induced cardiomyopathy." (PMID 33110475, 2020). "DOX can cause cardiotoxicity, cardiomyopathy, and congestive heart failure through inflammatory mechanisms and an increase in IL-8, NFκB, TNFα, monocyte chemotactic protein-1 (MCP-1), and Doxorubicin-mediated activation of NFκB and inflammatory cytokines by the effect of DOX through HMGB1." (PMID 35340325, 2022). "Thus, we speculated that HMGB1 might be involved in the protective effects of DXZ on DOX-induced cardiomyopathy." (PMID 34336950, 2021). "However, at present, it is not clear whether the protective effects of DXZ on DOX-induced cardiomyopathy are related to the regulation of HMGB1." (PMID 34336950, 2021). "In this study, DOX was used to induce the cardiomyopathy in rats, and it was found that DXZ had protective effects on DOX-induced cardiotoxicity, which was related to regulation of ferroptosis by targeting HMGB1." (PMID 34336950, 2021). "Idiopathic dilated cardiomyopathy is a clinical diagnosis by exclusion and no preclinical studies have examined HMGB1 in this condition in animal models of spontaneous cardiomyopathy." (PMID 30306212, 2019).
keratitis (13 papers, 2016 to 2025). A corneal disease that is characterized by inflammation of the cornea. "For example, antibody neutralization of HMGB1 also improved disease outcome of keratitis in P. aeruginosa infected susceptible mice." (PMID 29376148, 2016). "In keratitis models, HMGB1 has multiple functions involved in autocrine and paracrine positive feedback mechanisms." (PMID 38930536, 2024). "For example, LOX-1 inhibition results in a reduced pro-inflammatory response to DAMPs such as high-mobility group box 1 (HMGB1) in A. fumigatus keratitis." (PMID 36499260, 2022). "Work in a Pseudomonas aeruginosa keratitis model showed that glycyrrhizin, a HMGB1 inhibitor, significantly reduced HMGB1 levels and bacterial load." (PMID 31159195, 2019). "In P. aeruginosa-induced keratitis, elevated levels of extracellular HMGB1 exacerbate inflammation by stimulating neutrophils via RAGE and TLR pathways." (PMID 30473885, 2018). "Silencing HMGB1 in a mouse model of P. aeruginosa-induced keratitis increases levels of anti-inflammatory cytokines, reduces levels of inflammatory cytokines and neutrophil infiltration, and improves prognosis." (PMID 30473885, 2018). "Taken together, these pre-clinical anti-HMGB1 treatment strategies provide routes to develop therapeutics based upon reduction of HMGB1 levels, with the goal of using this strategy to clinically manage the adverse effects of HMGB1 in keratitis." (PMID 29376148, 2016). "HMGB1, an alert protein, amplified inflammation in P. aeruginosa-induced keratitis." (PMID 38930536, 2024). "In the mouse keratitis model, as in silencing HMGB1 (siRNA use), recombinant (r) TM, composed of TM domains 1-4, (Leu 17-Ser 517), treatment led to better clinical disease scores in treated mice after after infection and slightly (1 log) lessened the plate count in cornea." (PMID 34684184, 2021). "If monocytes and Mφ were affected by RNA interference of HMGB1 in the keratitis model was unknown and so after silencing HMGB1, we examined amounts of CXCL12 and CXCR4 (mRNA and protein); both were reduced vs. scrambled control levels." (PMID 34684184, 2021). "Attenuating HMGB1-mediated disease progression can help treat keratitis." (PMID 30473885, 2018). "Stromal infiltration by exogenous immune cells, migrating against gravity, occurred regardless of whether HCF were present in the construct, and also occurred in uninfected constructs exposed to rHMGB1 alone, consistent with a principal role for HMGB1 in adenovirus keratitis." (PMID 40367285, 2025). "The impact of PL on the expression of HMGB1, LOX-1, TNF-α, IL-1β, IL-6, IL-10 and ROS in A. fumigatus keratitis was investigated using RT-PCR, ELISA, Western blot, and Reactive oxygen species (ROS) assay." (PMID 38655086, 2024). "In P. aeruginosa induced keratitis, for example, GLY binds to HMGB1, inhibits inflammation and decreases bacterial load to provide better disease outcome." (PMID 36422579, 2022). "In vivo experiments showed that glycyrrhizin reduced the expression of HMGB1, TNF‐α and IL‐1β in osteoarthritic cartilage, as reported in keratitis and necrotizing enterocolitis." (PMID 34953035, 2022). "Likewise, another study showed that glycyrrhizin reduced HMGB1, TLR4, IL‐1β and IL‐12 and was protective against keratitis." (PMID 34953035, 2022). "When we tested the two agents in the keratitis model, GLY was better overall in decreasing HMGB1 expression (mRNA and protein) in KEI 1025 (a clinical isolate of P. aeruginosa)–infected corneas and decreased corneal disease better when compared with carbenoxolone." (PMID 34684184, 2021). "Glycyrrhizin reduces HMGB1 and is protective against P. aeruginosa–induced keratitis with a clinical isolate that is noncytotoxic." (PMID 27792814, 2016).
memory impairment (13 papers, 2015 to 2025). "Furthermore, mAb 1, mAb 2.5, and mAb 5 suppress second hit PTZ induced seizure and related memory impairment which might be due to an anti-inflammatory associated mechanism of mAb via the modulation of HMGB1/TLR4/NF-κB axis." (PMID 33732146, 2020). "Oral pretreatment of glycyrrhizin inhibited HMGB1 cytosolic expression, alleviates the surgery-Induced HMGB1 upregulation in the hippocampus of the mice and attenuated the severity of post-operative memory impairment, as evidenced by the shorter swimming latency and distance in MWM trials." (PMID 30271319, 2018). "Therefore, HMGB1 may be an important reason for NLRP3 inflammasome-induced memory impairment in the late stage of TBI." (PMID 34666797, 2021). "Some in vitro research has suggested that the HMGB1-RAGE-TLR4 signaling pathway worsens hippocampal injury, contributing to memory impairment in patients with AD." (PMID 39796257, 2025). "It has been shown that increased expression of HMGB1 correlates with elevated levels of RAGE and contributes to memory impairment, demyelination, and neurodegeneration." (PMID 26733811, 2015). "For example, the cytokine high-mobility group box 1 (HMGB1) is elevated in plasma samples of GWI patients and intraperitoneally (i.p.)administered HMGB1 has been shown to activate microglia and produce memory impairments and depressive-like behavior in mice." (PMID 38919622, 2024). "More precisely, inhibiting HMGB1/RAGE/TLR4 pathway represents a promising approach which can interfere with disease progression in epileptogenesis, neuroinflammatory disease, several forms of brain injury as well as memory impairment." (PMID 30271319, 2018). "Several drugs exert their pharmacological effects through the inhibition of various molecules within the HMGB1/TLR4/NF-κB pathway, resulting in reduced hippocampal inflammatory responses, suppressed microglial activation, mitigated neuronal injury and attenuated surgery-induced memory impairment." (PMID 38975244, 2024).
metabolic syndrome (13 papers, 2018 to 2026). A cluster of metabolic risk factors for CARDIOVASCULAR DISEASES and TYPE 2 DIABETES MELLITUS. "This study identified lipid aggregation product (LAP), TNF-α, and HMGB1 as useful predictors of metabolic syndrome, with LAP showing the highest diagnostic value." (PMID 40871683, 2025). "Atrial HMGB1 was normalized after RDN in this study, providing evidence for a systemic sympathoadrenergic mediated HMGB1 regulation in metabolic syndrome." (PMID 35834066, 2022). "HMGB1 was increased in both left and right atrial tissue in metabolic syndrome, indicating activation of RAGE with consecutive activation of pro-inflammatory signal transduction pathways." (PMID 35834066, 2022). "A clue was the link between PV and metabolic syndrome and HMGB1 high levels in obese patients." (PMID 35053208, 2021).
peritonitis (13 papers, 2013 to 2026). Inflammation of the peritoneum (tissue that lines the abdominal wall and covers most of the organs in the abdomen). "Our results showed that expression level of acetyl-HMGB1 was increased in visceral peritoneum tissue of LPS-associated peritonitis, compared to the control group." (PMID 30539006, 2018). "Inhibition of HMGB1 augmented peritoneal inflammation and improved peritoneal function in LPS-associated peritonitis in mice." (PMID 23359306, 2013). "All these findings intrigued us to speculate that the pathogenic effect of HMGB1 might contribute to its acetylation in PD-related peritonitis." (PMID 30539006, 2018). "In summary, the present study suggests that elevated acetylation of HMGB1 in PD-associated peritonitis may promote peritoneal mesothelial cell apoptosis." (PMID 30539006, 2018). "A study showed potential association of miR-146a with HMGB1 in a peritonitis model." (PMID 26997759, 2016). "In line with previous studies, our results also showed that inhibition of HMGB1 by glycyrrhizin significantly attenuated LPS-induced peritoneal inflammatory cells infiltration and improved peritoneal function in mice, supporting the potential pathogenic role of HMGB1 in LPS-associated peritonitis." (PMID 23359306, 2013). "The present study demonstrates elevated acetylation of HMGB1 protein in PDE of patients with peritonitis and its impact in peritoneal mesothelial cell apoptosis." (PMID 30539006, 2018). "Our previous study revealed an elevated HMGB1 protein in the peritoneal dialysis effluence (PDE) of patients with peritonitis." (PMID 30539006, 2018). "We previous reported that HMGB1 levels in PDE were higher in patients with peritonitis than those in controls, and gradually declined during the period of effective antibiotic treatments." (PMID 30539006, 2018). "Here, we showed that LPS treatment led to increased protein level of acetylated HMGB1, concomitant with elevation in peritoneal mesothelial cell apoptosis, in both acute peritonitis mice model and HMrSV5 cells stimulated by LPS." (PMID 30539006, 2018). "Given the link between acetylated HMGB1 and peritonitis, we sought to explore the contribution of peritoneal mesothelial cells in increased acetylated HMGB1 during PD-related peritonitis, using acute peritonitis mice model and HMrSV5 cells treated with LPS." (PMID 30539006, 2018). "Treatment with HMGB1 antagonists ameliorates acute peritoneal inflammation and membrane dysfunction in the animal model of LPS-induced peritonitis." (PMID 30539006, 2018). "In the present study, we confirmed that acetylated HMGB1 in PDE of patients with clinical peritonitis were significantly increased compared to those in control subjects." (PMID 30539006, 2018). "Increased HMGB1 protein expression has been observed in the rat diaphragm with peritonitis, which was accompanied by signs of severe oxidative stress and contractile dysfunction." (PMID 26161253, 2015). "We also explored the effect of HMGB1 on peritoneal function in LPS-induced peritonitis in mice and further examined the source and the process of HMGB1 release using human peritoneal mesothelial cell line (HMrSV5) in vitro." (PMID 23359306, 2013). "The results showed that the levels of HMGB1 in PDE were higher in patients with peritonitis than those in controls, and gradually declined during the period of effective antibiotic treatments." (PMID 23359306, 2013). "The levels of HMGB1 were significantly elevated in PDE samples of patients with peritonitis as compared with the controls." (PMID 23359306, 2013). "By animal model, inhibition of HMGB1 with glycyrrhizin was performed to determine the effects of HMGB1 in LPS-induced mice peritonitis." (PMID 23359306, 2013). "Our study showed that PDE HMGB1 levels in patients with peritonitis were significantly higher than those in control subjects and correspondingly elevated levels decreased gradually after effective antibiotic treatment." (PMID 23359306, 2013).